DAG1 (dystroglycan 1)
Diseases named in the same sentence as DAG1 in open-access papers (continued):
Sharing a sentence is not in itself a finding about the gene and the disease.
limb-girdle muscular dystrophy (3 papers, 2015 to 2023). Limb-girdle muscular dystrophy (LGMD) is a heterogeneous group of muscular dystrophies characterized by proximal weakness affecting the pelvic and shoulder girdles. "A point mutation, T192-M, in the DAG1 gene has also been identified in a human patient with limb-girdle muscular dystrophy and a mouse model carrying this mutation recapitulates the abnormalities in human." (PMID 33969874, 2021).
Lissencephaly (3 papers, 2011 to 2024). A spectrum of malformations of cortical development caused by insufficient neuronal migration that subsumes the terms agyria, pachygyria and subcortical band heterotopia. "Such mixed glial and neuronal heterotopias are also reminiscent of those observed in postmortem cases of type-II lissencephaly, as well as mice with Dag1 mutations." (PMID 22028625, 2011). "Central to cobblestone lissencephaly hypotheses is post-translational regulation of dystroglycan (coded by DAG1, dystrophin-associated glycoprotein 1), a glycoprotein present in RG basal processes, that acts as an anchor point with the ECM, being also important for BM structure." (PMID 33178693, 2020). "In neocortex, Dag1 expression in radial glia is required for proper migration of neurons, with Dag1 conditional deletion from neuroepithelial cells or radial glia resulting in Type II lissencephaly." (PMID 38179984, 2024).
diabetes (2 papers, 2015 to 2018). "It is likely that the difference in expression of the lymphocyte-enriched genes Psmc2, Dag1 and Tbk1 in mice with early or late diabetes onset was under-estimated by the analysis in whole blood, in which lymphocytes are under-represented." (PMID 26366287, 2015). "The gene most significantly correlated with age of diabetes onset was Dag1 (r=0.976, P<1e−07)." (PMID 26366287, 2015).
Hypertension (2 papers, 2025). The presence of chronic increased pressure in the systemic arterial system. "In conclusion, hypertension altered processes related to central nervous system development, inflammation and blood coagulation (including YKL-40, KNG1, DAG1, and the SERPIN family)." (PMID 41152331, 2025).
muscular dystrophy-dystroglycanopathies (2 papers, 2021 to 2024). "The DAG1 gene is also linked to Muscular dystrophy-dystroglycanopathy (congenital with brain and eye anomalies, OMIM #616538)." (PMID 34976016, 2021).
astrocytoma (1 paper, 2019). "This revealed that DAG1 tended to correlate with tumour grade, as expression was highest in GBM compared to oligodendroglioma and astrocytoma cases, while all tumour types were elevated above normal brain tissue (Online Resource 1b)." (PMID 31463571, 2019).
brain cancer (1 paper, 2019). A primary or metastatic malignant neoplasm affecting the brain. "To determine if DAG1 was important in the context of brain cancer we interrogated both the Rembrandt and TCGA databases to correlate DAG1 gene expression with survival." (PMID 31463571, 2019). "The Rembrandt database was also used to assess DAG1 gene expression in GBM as well as other forms of malignant brain cancer versus normal brain tissue." (PMID 31463571, 2019).
clear cell renal cell carcinoma (1 paper, 2022). "Among the identified potential tumor suppressor genes, DAG1 was co-deleted with the Von Hippel Lindau (VHL) tumor suppressor gene in clear cell renal cell carcinoma." (PMID 36499305, 2022).
cobblestone lissencephaly (1 paper, 2012). "Aberrant glycosylation of α-dystroglycan causes human cobblestone lissencephaly, whereas deleting the mouse Dag1 gene results in early embryonic lethality." (PMID 22235340, 2012).
dementia (1 paper, 2018). Loss of intellectual abilities interfering with an individual's social and occupational functions. "Using human transcriptomic data, we demonstrate that expression of perivascular astroglial gene products dystroglycan (DAG1), dystrobrevin (DTNA) and alpha-syntrophin (SNTA1), are associated with dementia status and phosphorylated tau (P-tau) levels in temporal cortex." (PMID 30120299, 2018). "Like the established DAC genes AQP4, DTNA, DAG1 and DMD, expression of several endfoot candidate genes differed between dementia-free and subjects with dementia." (PMID 30120299, 2018).
depression (1 paper, 2025). "We have identified six protein-coding genes associated with depression and primarily involved in inflammation (TNXB), neuroplasticity (NCAM1 and LTBP3), immune response (BTN3A2), cell survival (DAG1) and circadian clock modification (FHIT)." (PMID 39897774, 2025). "The present study identified six protein-coding genes associated with depression and primarily involved in inflammation (TNXB), neuroplasticity (NCAM1 and LTBP3), immune response (BTN3A2), cell survival (DAG1) and circadian clock modification (FHIT)." (PMID 39897774, 2025). "Eight SNPs corresponding to six protein-coding genes (TNXB, NCAM1, LTBP3, BTN3A2, DAG1, FHIT) were identified that were highly associated with depression." (PMID 39897774, 2025). "Our findings confirmed previous evidence for TNXB- and NCAM1 in the pathophysiology of depression and suggested four new potential candidate genes (LTBP3, BTN3A2, DAG1 and FHIT) that warrant further investigation." (PMID 39897774, 2025). "Our findings confirmed previous evidence for TNXB- and NCAM1 in the pathophysiology of depression and suggested new potential candidate genes (LTBP3, BTN3A2, DAG1 and FHIT) that warrant further investigation." (PMID 39897774, 2025). "Other potential candidate genes whose function might provide new insights in the pathophysiological process of depression include LTBP3, BTN3A2, DAG1 and FHIT." (PMID 39897774, 2025).
glioblastoma (1 paper, 2022). The most malignant astrocytic tumor (WHO grade IV). "In glioblastomas, DAG1 correlated with tumor grade, and the patient group with higher expression of DAG1 survived for a shorter time than the patient group with lower expression of DAG1." (PMID 36499305, 2022).
leukemia (1 paper, 2022). A malignant (clonal) hematologic disorder, involving hematopoietic stem cells and characterized by the presence of primitive or atypical myeloid or lymphoid cells in the bone marrow and the blood. "Here, the DAG1 mRNA was found to be downregulated (by −2.17-fold) in leukemia primary blasts with different degrees of maturation (subtypes M1, M2 and M3), as compared to control (CD34+) stem-progenitor cells from healthy individuals." (PMID 36494657, 2022). "Also, decreased expression levels were observed in the HL-60 and Kasumi-1 leukemia-derived cell lines of α-DG core protein (by ‒ 1.28- and ‒ 2.00-fold, respectively), and especially of β-DG (by ‒ 6.25- and ‒ 2.17-fold), correlating with an underexpression of DAG1 mRNA (by ‒ 2.50- and ‒ 1.49-fold)." (PMID 36494657, 2022).
myocardial infarction (1 paper, 2021). Gross necrosis of the myocardium, as a result of interruption of the blood supply to the area, as in coronary thrombosis. "Agrin promotes cardiomyocyte proliferation in post-myocardial infarction hearts through DAG1 and YAP and in our study we observed a requirement for agrin to ensure YAP activation in the context of epicardial EMT." (PMID 33969874, 2021).
ovarian tumor (1 paper, 2020). "In the library prepared from ovarian tumor tissue, 5 clones with coding sequences were identified using the HMGB1 bait (C1QA, DAG1, RPL29, RSF1, TGM2), and 6 (COMMD1, MIEN1, PCBP1, TBC1D25, ZFR, ZNF428) were identified with the HMGB2 bait." (PMID 32867128, 2020).
thymic lymphoma (1 paper, 2019). "All DAG1 KD animals developed spontaneous thymic lymphoma, which is a common occurrence in this strain, and were euthanised as per our ethical guidelines." (PMID 31463571, 2019).
tumor (16 papers, 2003 to 2025). "Consequently, a tumor-suppressing role has been explicitly proposed for DAG1 and some of the DGP-associated genes." (PMID 36494657, 2022). "DAG1 was reported to function as a tumor suppressor and repress the progression of several cancers, including EC." (PMID 37014625, 2023). "The identified potential tumor suppressor genes included DAG1, SLC39A8, TMEM173/STING1, RDX, TJP1, CTNNB1, and SMC3." (PMID 36499305, 2022). "qPCR analysis of post-mortem tumour tissue confirmed a significant (p < 0.01) reduction in DAG1 mRNA levels compared to control shRNA engrafted animals (Online Resource 6c)." (PMID 31463571, 2019). "Positive tumour formation was confirmed by haematoxylin and eosin (H&E) staining in all control and DAG1 KD engrafted animals (Online Resource 6d)." (PMID 31463571, 2019). "To assess the relative mRNA levels of DAG1 in GBM we performed QPCR on 28 GBM tumour specimens from our in-house tumour bank." (PMID 31463571, 2019). "In EC, DAG1 expression was significantly downregulated, promoting the progression of the tumor." (PMID 37014625, 2023). "Furthermore, LGALS9 secreted from TAM facilitated tumor migration and maintenance of extracellular matrix homeostasis by binding to DAG1 on GSCL and Class-G cells." (PMID 37964983, 2023). "We found that DAG1 expression in several cell lines did not correlate with tumour cell line and tumour graft susceptibility using the GP of low affinity variant HPI WT (Y155H) in an oncolytic VSV-based platform (VSV-GP)." (PMID 34648606, 2021). "We noted that the neutrophils from tumors generated in qMCP−/−; Ntv-a mice appeared to be enriched in interactions with many tumor clusters (T0, and T2 to T5) through secretion of tumor necrosis factor α (TNF-α) and signaling via TNF-α receptor-I (TNFR-I: p55) and DAG1 on tumor cells." (PMID 37012245, 2023). "To date, the literature supports the tumor suppressor functions of DAG1, SLC39A8, TMEM173/STING1, TJP1, CTNNB1, and SMC3, but not RDX." (PMID 36499305, 2022). "Specifically, a co-upregulation of CDK7 and DAG1 was observed in normal lung B cells, but not in the tumor B cells (p < 0.05, one-tailed z-tests)." (PMID 35804895, 2022). "In-vivo DAG1 KD studies were conducted using two models, WK1 (CL) and JK2 (MES), in the later mesenchymal model no tumours were detected in all DAG1 KD animals including a single animal which survived for 598 days post engraftment." (PMID 31463571, 2019). "Positive tumour formation was confirmed by H&E staining in all control shRNA engrafted animals, while no clinical signs of intracranial tumour formation were observed in DAG1 KD animals or intracranial tumour detected by H&E staining post-mortem." (PMID 31463571, 2019). "Furthermore, we showed that ABCC4, DAG1, and SLC39A8 proteins are significantly downregulated in tumors compared to NATs, suggesting that they may play the role of tumor suppressors." (PMID 36499305, 2022).
cancer (13 papers, 2003 to 2025). A tumor composed of atypical neoplastic, often pleomorphic cells that invade other tissues. "The highly expressed TNF in macrophages in the S components was associated with upregulated DAG1 in cancer cells, which regulated cell growth and apoptosis." (PMID 35874770, 2022). "We found that 30 of these genes which included Nckap1l, Ncf1, Pla2g15, Unc93b1, Lrrc33, Rgs10, Gmfg, Rbm25, C3ar1, Ccdc88b, Fam105a, Gng11, Phc1, Rasa4, Dag1, Tyrobp, Tmsb4x, Cfp, Prkd1, Gp49a, Trem2, C1qc, Lyz2, Igfbp7, Rab30, Cxcl16, Egfl7, Ube2r2, Pltp, and Cfb, showed a relation with cancer." (PMID 32812032, 2020). "Common fragile site genes (DAG1 and PARK2) and various genes that have elevated expression patterns in cancers are also connected in these networks." (PMID 21884569, 2011). "The hAG/DAG-1 interaction could therefore have more of a paracrine function than the hAG/C4.4a interaction, and thus be involved in cell–cell interactions between cancer and noncancer cells and the intervening extracellular matrix." (PMID 12592373, 2003).
infection (8 papers, 2017 to 2025). The state of being infected such as from the introduction of a foreign agent such as serum, vaccine, antigenic substance or organism. "Although α-dystroglycan (DAG1) was long recognized as the cell surface receptor for Lassa virus, additional factors were suspected, given the observation that certain DAG1-expressing cells are resistant to infection." (PMID 28321417, 2017). "However, not all LCMV variants are dependent on functional DAG1 for virus binding and infection." (PMID 34648606, 2021). "We speculated that reduced glycosylation of DAG1 can lead to reduced cell-matrix adhesion, ECM stiffness, and tissue integrity, similar to glycosylation roles in adhesion, cell communication, and infection of endothelial cells (right)." (PMID 38830841, 2024). "The natural absence of functional DAG1 makes the murine fibroblast cell line L929 a perfect model for LCMV-GP mediated DAG1-independent infection analysis and validation of results obtained with 293T cells." (PMID 34648606, 2021). "Expression of CMA genes during infection of these cell lines was also examined (right 12 lanes), and demonstrated that reduction in GRIM-19 level did not influence the level of transcription of any of the four CMA genes tested (TPM3, STX3, Dystroglycan 1 [DAG1], and Heme-binding protein 1 [HEBP1])." (PMID 34346763, 2021). "Unlike DAG1, to which LCMV strains show a range of affinities, all five LCMV strains tested here required CD164 for infection in human cells." (PMID 35502904, 2022).
DAG1 also shares sentences with these, for which no sentence is quoted: congenital muscular dystrophy (2 papers); Fukuyama congenital muscular dystrophy (2); gastric cancer (2); glioma (2); hemorrhagic fever (2); muscle-eye-brain disease (2); myopathy (2); myopia (2); ovarian carcinoma (2); psoriasis (2); Allgrove syndrome (1); Alzheimer disease (1); ankylosing spondylitis (1); Arrhythmia (1); Brugada syndrome (1); cervical cancer (1); Cognitive impairment (1); colon cancer (1); COVID-19 (1); esophageal squamous cell carcinoma (1); focal segmental glomerulosclerosis (1); GNE myopathy (1); hepatoma (1); Hyperglycemia (1); IgA nephropathy (1); keratoconus (1); Lassa fever (1); lymphoma (1); membranous glomerulonephritis (1); microcephaly (1).
A further 14 diseases each share a sentence with DAG1 in 1 paper.